TERT (telomerase reverse transcriptase)
Diseases named in the same sentence as TERT in open-access papers (continued):
Sharing a sentence is not in itself a finding about the gene and the disease.
oligodendroglioma (continued). "In particular, individuals with TERT promoter mutations demonstrated a more favorable prognosis compared to those with wildtype TERT promoter, specifically in grade II or III oligodendroglioma, 1p/19q-codeleted patients, and IDH-mutant cases." (PMID 37662954, 2023). "Thus, TERT promoter mutations are common in both the most and the least aggressive diffuse gliomas (IDH-wildtype diffuse astrocytomas and IDH-mutant and 1p19q-codeleted oligodendrogliomas, respectively), suggesting that TERT promoter mutations are not dictating their biological behavior." (PMID 29616301, 2018). "Defines oligodendroglioma lineage (ATRX intact, TERT-mut); these tumors are chemo-sensitive." (PMID 41346390, 2025). "Our patient’s tumor harbored mutations in TERT, FUBP1, and CIC, which are common alterations in oligodendroglioma, but not clinically relevant." (PMID 39857783, 2025). "Analysis of the SHAP values for the remaining genes revealed that increased expression of ZDHHC18, HDAC1, and TUBB6 enhances the probability of predicting astrocytoma, while elevated expression of TERT, TRIM67, NOG, KCNIP2, and KCNJ11 increases the probability of predicting oligodendroglioma." (PMID 40867242, 2025). "Subsequently, we investigated the overall performance of our MLPA cutoff criteria in association with the features typical for oligodendrogliomas (oligodendroglial histology, IDH and TERT mutations and no ATRX loss)." (PMID 29923492, 2018). "A majority of oligoastrocytomas (63.8%) exhibited the IDH mutation in the absence of TERT promoter mutations, much like Grade II-III astrocytomas; however, a fraction (22.4%) of oligoastrocytomas presented with both TERT promoter and IDH1/2 mutations, similar to oligodendrogliomas." (PMID 24722048, 2014).
astrocytomas (114 papers, 2014 to 2026). "In comparison, profiling the molecular characteristics of H3-wildtype-astrocytomas and ependymomas through CSF detection remains challenging, including the identification of specific driver mutations like TERT promoter mutations." (PMID 38388726, 2024). "In contrast, TERT mutation has been significantly associated with better survival in IDH-mutant astrocytomas and 1p/19q-codeleted oligodendrogliomas." (PMID 38240992, 2024). "Specifically, TERT promoter mutation has been significantly associated with worse survival in IDH-wildtype astrocytomas." (PMID 38240992, 2024). "TERT promoter mutations were observed in both H3 K27M-mutant (4/25) and -wildtype (9/33) astrocytomas, and were associated with a poor prognosis in H3-wildtype histological grade II/III astrocytomas." (PMID 32228694, 2020). "One mGBM patient with histological grade II astrocytoma and TERT mutation is still alive at 62 months, and he was treated with subtotal resection followed by RT alone without chemotherapy." (PMID 33235995, 2020). "We identified two subtypes of IDH wild-type astrocytoma, one was enriched for astrocytomas with TERT promoter mutation and showed high expression of chemokine signaling pathway genes." (PMID 29221210, 2017). "We found IDH mutations in 30.30% of astrocytomas samples and 51.51% for TERT mutations, with one sample having both mutations." (PMID 29221210, 2017). "Samples of astrocytomas with MGMT promoter methylation had less TERT mutations than samples with low MGMT promoter methylation (p=0.041)." (PMID 29221210, 2017). "In conclusion, we performed, for the first time, an integrated characterization of chromosomal CNA, microsatellite instability, and TERT/IDH1 mutational analysis in astrocytomas arising in the Brazilian population." (PMID 27172220, 2016). "Further, we also investigated the independent effect of 1p/19q codeletions, IDH mutations and TERT promoter mutations in astrocytomas." (PMID 25797251, 2015). "Here, patients with astrocytomas harboring TERT promoter mutations showed a median survival of 29.7 months compared to 107.9 months when mutations were not present." (PMID 25797251, 2015). "In patients with astrocytoma, the TERT promoter mutations only associated with poor survival (P < 0.0001); IDH mutations and 1p/19q deletions associated with increased survival (P = 0.0004)." (PMID 25797251, 2015). "In astrocytomas, where both, TERT promoter and IDH mutations, were frequent, the OR of 0.60 suggested an inverse association; however this observation was not statistically significant." (PMID 25797251, 2015). "Conversely, IDH1/2 mutations in Grade II-III astrocytomas are frequent while TERT promoter mutations are uncommon." (PMID 24722048, 2014). "In particular, 13.6% (12/88) of Grade II-III astrocytomas bore TERT promoter mutations alone and occasional Grade II-III astrocytomas harbored both TERT promoter and IDH1/2 mutations (4/88, 4.6%)." (PMID 24722048, 2014). "In the cohort of the IDH-wt astrocytomas the TERT promoter was mutated in 28 of 41 analyzed patients (68.3%); EGFR amplification was detected in 23 out of 48 analyzed patients (47.9%); and nuclear ATRX loss was detected in 12 (9.6%) patients, while it was retained in 113 (90.4%)." (PMID 41466163, 2025). "Interestingly, TERT promoter mutations have a better prognosis in the presence of K27M mutations in grades 2 and 3 astrocytomas." (PMID 41154124, 2025). "IDH1/2 wt astrocytomas, with TERT mutation only, have the highest age of onset (62 years)." (PMID 38326661, 2024).
astrocytomas (continued). "Third, IDH wild-type astrocytomas with TERT promoter mutations, EGFR amplification, and + 7/− 10 chromosome copy number changes need to be further considered in future study to fully elucidate the intratumoral heterogeneity of IDH wild-type GBM according to the WHO CNS5." (PMID 37993907, 2023). "The only exceptions are also the presence of CDKN2A/B homozygous deletion for IDHm astrocytoma, and of TERT promoter mutation, EGFR gene amplification, and chromosome 7 gain/chromosome 10 loss for IDH wild-type diffuse astrocytomas, which classify them as grade IV, which were missing in our study." (PMID 37534252, 2023). "In astrocytomas, TERT promoter and IDH mutations were both found in only 2 of 15 cases." (PMID 34558656, 2022). "Similarly, the astrocytoma patients with TERT promoter mutations or long RTL were also resistant to radiotherapy." (PMID 26556853, 2016). "Additionally, the poor prognosis of grade II astrocytomas with TERT promoter mutations suggests that these tumors can be classified into an aggressive subtype." (PMID 24937153, 2014). "The effect of TERT promoter mutations on survival was examined in astrocytoma (grade II) patients." (PMID 24937153, 2014). "Therefore, undiagnosed IDH1/2 wt astrocytomas with TERT mutation only might impact our cohort's tendency towards a higher age of onset." (PMID 38326661, 2024). "A more recent study showed that GBM (IDH-Wildtype) is associated with TERT promoter mutations in 89% of the cases, compared to only 20% in IDH-Mutant astrocytomas." (PMID 39273661, 2024). "The astrocytomas commonly have loss of α-thalassemia mental retardation X-linked (ATRX), which is retained in oligodendrogliomas, and astrocytomas frequently have TERT promoter mutations." (PMID 36428772, 2022). "According to cIMPACT-NOW update 3, IDH-wild-type astrocytomas with any of the following factors show poor prognosis: combination of chromosome 7 gain and 10 loss (+ 7/− 10), and/or EGFR amplification, and/or TERT promoter (TERTp) mutation." (PMID 34257410, 2021). "Among the 55 astrocytoma IDH wt tumors, all five IDH wt, WHO grade II tumors had mutations that altered telomere function, including four that had TERT promoter (pTERT) mutations, and one that had an ATRX truncating mutation." (PMID 31167453, 2019). "TERT mutation only cases (that means IDH-WT astrocytomas) were the worst prognostic group and that group had worse survival than that of patient with IDH-WT and TERT-WT." (PMID 28851427, 2017). "In the present study, we performed a molecular characterization in order to describe the genomic alterations and mutation status of the key TERT and IDH1 genes in astrocytomas arising in the Brazilian population." (PMID 27172220, 2016). "A total of 69% of GBMs presented TERT mutation, whereas IDH1 mutation was most frequent in diffuse (85.7%) and anaplastic (100%) astrocytomas." (PMID 27172220, 2016). "ATRX was mutated in only one case (IDH-mutant astrocytoma), while no mutation of the TERT promoter was found." (PMID 41517303, 2025). "In contrast, the TERT promoter was pertinent exclusively to IDH wildtype astrocytoma." (PMID 37537630, 2023).
astrocytomas (continued). "Second, the current cohort included IDH wild‐type histologically diagnosed GBMs but lacked IDH wild‐type astrocytomas that were positive for TERT promoter mutations, EGFR amplification, or + 7/−10 chromosome copy number changes." (PMID 37222229, 2023). "Furthermore, this pattern had a high frequency of 52.4% in IDHwt astrocytomas, meeting the definition of molecular GBM with only TERT promoter mutations." (PMID 36646712, 2023). "However, the subgroup of IDHwt astrocytomas included in our previous study was limited given its small sample size of only 20 patients and missing TERT status." (PMID 34902093, 2022). "mGBM was defined as grade II-III IDH-wildtype astrocytoma without histological features of GBM but with one of the following molecular alterations: TERT mutation, EGFR amplification, or combination of whole chromosome 7 gain and whole chromosome 10 loss." (PMID 33235995, 2020). "In patients diagnosed with histological grade II/III astrocytomas without the H3 K27M mutation, TERT promoter mutation was an indicator of poor prognosis (P = 0.013)." (PMID 32228694, 2020). "The group with mutation in IDH but not TERT (Group B) mostly consisted of astrocytomas and grade II-III oligoastrocytomas." (PMID 27503138, 2016). "Patients with astrocytomas were also grouped according to their TERT promoter and IDH status." (PMID 25797251, 2015). "Therefore, the aim of this study was to characterize the genomic profile of 65 Brazilian astrocytomas, using aCGH and MSI, as well as to associate these data with the mutational status of the TERT promoter and IDH1 genes, and clinico-pathological features of the patients." (PMID 27172220, 2016). "Therefore, when considering the prognosis of spine astrocytoma with TERT promoter mutations, it is crucial to take into account the combined molecular profile of the tumor rather than solely relying on the presence of TERT mutations." (PMID 41154124, 2025). "Therefore, we performed CNA profiling of 65 astrocytomas of distinct malignant grades (WHO grade I–IV) of Brazilian origin, using array-CGH and microsatellite instability analysis (MSI), and investigated their correlation with TERT and IDH1 mutational status and clinico-pathological features." (PMID 27172220, 2016). "To prove specificity of the assay, we assayed an IDH-mutant astrocytoma with wildtype TERTp and detected no TERT mRNA expression." (PMID 36114166, 2022). "We observed that 2/60 (3%) IDHmut astrocytomas were reclassified as A4IDHmut due to CDKN2A/B homozygous deletion and 5/60 (8%) of IDHwt grades 2 and 3 were reclassified as GBMs (grade 4) due to one or more alterations in TERT, EGFR, and chromosomes 7 and 10, under the 2021 WHO criteria." (PMID 38672598, 2024). "Virtually all ALTpositive astrocytomas had normal TERT promoter and lacked ATRX expression." (PMID 31960234, 2020).
meningioma (110 papers, 2013 to 2026). A generally slow growing tumor attached to the dura mater. "In recent years, TERT promoter mutations have been identified as crucial molecular markers associated with tumor recurrence and poor prognosis, especially in higher-grade meningiomas." (PMID 41013491, 2025). "Particularly, any meningioma with CDKN2A/B homozygous deletion or TERT promoter mutation should be diagnosed as WHO grade 3, regardless of histological criteria of anaplasia." (PMID 39991581, 2025). "In terms of clinical behavior, a few rare molecular alterations have been linked to aggressive meningioma biology, including oncogenic variants in the TERT promoter region and homozygous deletions of CDKN2A/CDKN2B." (PMID 40951339, 2025). "Emerging data suggest that molecular and epigenetic features—including CDKN2A deletion, TERT promoter mutation, copy number analyses, and methylation-based classification—will be important to integrate into risk stratification frameworks for meningioma." (PMID 41497451, 2025). "Multiple studies have demonstrated that the presence of TERT promoter mutation in meningiomas correlates with a poorer prognosis and reduced OS regardless of the WHO grades." (PMID 38758750, 2024). "Telomerase reverse transcriptase (TERT) promoter mutations present another useful biomarker in meningioma diagnostics." (PMID 39273576, 2024). "As a result, we cannot guarantee the exclusion of the group classified as having grade 3 anaplastic meningioma in 2021 based on TERT mutation or CDKN2A/B homozygous deletion." (PMID 38369575, 2024). "Herein, we screened histologically defined grade 2 meningiomas and only found one TERT promoter mutation and one homozygous CDKN2A/B deletion during our molecular testing (< 1% of analyzed tumors)." (PMID 38720399, 2024). "Publication of the WHO 2021 criteria has officially moved meningioma grading into the molecular era, with recognition of the independent prognostic implications of TERT promoter mutations and CDKN2A/B deletions." (PMID 37675219, 2023). "Activating TERT promoter mutations have been detected frequently in high-grade meningiomas and low-grade meningiomas that subsequently undergo malignant progression." (PMID 36836440, 2023). "The World Health Organization (WHO) classifies meningiomas based on mitotic activity, brain invasion, TERT promoter mutations, and other neuropathological characteristics." (PMID 37370707, 2023). "In conclusion, we revealed radiomics to reliably predict TERT promotor mutations in high-grade meningiomas with good to excellent discriminatory performance." (PMID 37686690, 2023). "Although providing analyzes in a considerable cohort size of high-grade meningiomas, our study suffers from its retrospective nature and limitations due to the low frequency of TERT promoter mutations." (PMID 37686690, 2023). "VEGF, EGFR, EGFRvIII, PD-L1; and Sox2 expression; MGMT methylation status; and TERT promoter mutation were assessed in paired meningioma samples collected from the same patient before and after progression using immunohistochemistry and PCR." (PMID 36836440, 2023). "In meningiomas, mutations of the Telomerase Reverse Transcriptase (TERT) promotor have been detected in a small subset (<5–15%) of tumors with considerable worse prognosis." (PMID 37686690, 2023). "For example, meningiomas with a telomerase reverse transcriptase (TERT) promoter mutation or a homozygous deletion of CDKN2A and/or CDKN2B are classified as WHO grade 3." (PMID 37675219, 2023). "Mutations in TERT are most common in high grade meningioma, which contain fewer targetable mutations when compared to low grade meningioma, however, such mutations are predicted to be neoantigens." (PMID 37860270, 2023). "According to the latest grading criteria, meningiomas should be classified as WHO grade 3 whenever telomerase reverse transcriptase (TERT) promoter mutations and/or cyclin-dependent kinase inhibitor 2 A/B(CDKN2A/B) pure deletions are present." (PMID 37529695, 2023).